RBM12B (RNA binding motif protein 12B)
Synonyms: MGC:33837
Tractability: PROTAC: UniProt records ubiquitination sites on it; ubiquitination databases record sites on it; its protein half-life has been measured.
Gene: Protein-coding gene on chromosome 8 (93,728,155 to 93,741,098, reverse strand). Ensembl gene ENSG00000183808.
Subcellular location (Human Protein Atlas): Nucleoplasm
Gene Ontology:
Molecular function: protein binding; RNA binding; nucleic acid binding
Biological process: regulation of RNA splicing
Cellular component: nucleoplasm; ribonucleoprotein complex
Genetic constraint (gnomAD): Loss-of-function variants: 12 observed, 37.21 expected, observed/expected ratio (o/e) 0.32, 90% interval 0.21 to 0.52. The upper end of that interval is the gene's LOEUF score, 0.52, which puts it in group 2 of 6, group 1 being the genes least tolerant of losing a copy. Missense variants: 1,139 observed, 1,323 expected, observed/expected ratio (o/e) 0.86, 90% interval 0.82 to 0.9. Synonymous variants: 477 observed, 454.02 expected, observed/expected ratio (o/e) 1.05, 90% interval 0.97 to 1.13.
Homologues: Orthologues: macaque RBM12B (99% identical), chimpanzee RBM12B (87% identical), dog RBM12B (84% identical), pig RBM12B (84% identical), guinea pig RBM12B (80% identical), rabbit RBM12B (77% identical), mouse Rbm12b2 (63% identical), rat LOC120102832 (63% identical), rat Rbm12b (63% identical), mouse Rbm12b1 (63% identical), tropical clawed frog rbm12b.2 (29% identical), zebrafish rbm12bb (23% identical), and 8 more. Paralogues in human: RBM12 (28% identical), ESRP2 (11% identical), ESRP1 (10% identical), HNRNPH1 (10% identical), HNRNPH2 (10% identical), HNRNPF (9% identical), GRSF1 (8% identical), HNRNPH3 (7% identical).
Diseases named in the same sentence as RBM12B in open-access papers:
RBM12B is named in the same sentence as 2 diseases in open-access papers, as found by Europe PMC text mining. Sharing a sentence is not in itself a finding about the gene and the disease. The quoted sentences say what the papers report.
breast carcinoma (1 paper, 2019). "Collectively, this study presents novel evidence suggesting that TMEM68, IMPAD1, SDCBP, and RBM12B are potential modifiers of human breast cancer risk and outcome." (PMID 30914425, 2019).
RBM12B also shares sentences with these, for which no sentence is quoted: sarcoidosis (1 paper).